MTOR (mechanistic target of rapamycin kinase)
Diseases named in the same sentence as MTOR in open-access papers (continued):
Sharing a sentence is not in itself a finding about the gene and the disease.
breast cancer (continued). "The last of the discussed differentiating genes is mTOR, whose overexpression we demonstrated in breast cancer samples compared to the control." (PMID 39850811, 2024). "According to our data, there is a significant upregulation of Beclin1 as well as a significant down-regulation of mTOR at mRNA levels in tissue biopsies of breast cancer which can indicate the activation of the autophagy pathway in breast tumor tissues." (PMID 38164366, 2024). "CNV-altered ceRNET-associated mRNAs in breast cancer were shown to have a biological function and pathway enrichment for Focal Adhesion Kinase FAK-PI3K-Akt–mTOR-signaling." (PMID 38473871, 2024). "Together, these genes highlight the importance of the PI3K/AKT/mTOR pathway in breast cancer biology and treatment strategies." (PMID 39850811, 2024). "FASN enhanced proliferation and metastasis of breast cancer cells by attenuating the activation of AMPK/mTOR pathway, thereby impacting the sensitivity of chemotherapy or radiotherapy for breast cancer." (PMID 38408962, 2024). "As a result, PI3K/AKT/mTOR inhibitors are being tested to improve treatment outcomes for breast cancer patients, especially those with endocrine resistance." (PMID 39770406, 2024). "In breast cancer, the activation of the PI3K/AKT/mTOR pathway has been reported to be associated with increased resistance to chemotherapy." (PMID 38668383, 2024). "The PI3K/Akt/mTOR signaling pathway is a dominant factor in the endocrine resistance of breast cancer." (PMID 38339428, 2024). "Triple-negative breast cancer (TNBC), a form of breast cancer that is more aggressive and has a higher susceptibility for metastases, has been reported to have mutations in the PI3K/Akt/mTOR pathway in 25% of cases." (PMID 38892329, 2024). "Ser-104 was reported to be targeted by mTOR in breast cancer and to stimulate estrogen/ERα-mediated gene expression." (PMID 37171559, 2024). "PAICS, a key enzyme for de novo purine synthesis, activates the cAmp/PKA signaling pathway, promotes mTOR activity, activates estrogen receptor alpha, and enhances estrogen dependence and tamoxifen resistance in breast cancer." (PMID 39256367, 2024). "Recent research indicates a potential link between the PI3K/AKT/mTOR pathway and acquired resistance to endocrine therapy in HR+ breast cancer." (PMID 38339303, 2024). "This is a downstream marker of mTOR activation and predicts lower survival in breast cancer patients with high expression of hormone receptor-positive breast cancer undergoing endocrine therapy." (PMID 39544302, 2024). "Dysregulation of the PI3K/AKT/mTOR pathway in breast cancer plays a critical role in resistance to standard therapies." (PMID 39796647, 2024). "It has been reported that the combined use of CDK4/6 inhibitors and mTOR inhibitors can provide greater benefits to patients in the treatment of breast cancer." (PMID 38890443, 2024). "Previous studies have demonstrated that both Hippo and AKT/mTOR signaling pathways are involved in maintaining breast cancer stemness." (PMID 38504374, 2024). "The dysregulation of the PI3K/AKT/mTOR pathway is associated with tumor progression and resistance to HER2-targeted therapies in breast cancer." (PMID 38542136, 2024). "In breast cancer cells, through the mTOR pathway by specifically targeting HK2, miR-216b promotes autophagy and apoptosis." (PMID 39224810, 2024). "Taken together, RPN1 promotes the proliferation, migration, and invasion of breast cancer cells via the PI3K/AKT/mTOR signaling pathway." (PMID 38302629, 2024). "In breast cancer cells, diosgenin, a traditional Chinese medicine monomer, has been proven to inhibit Akt and mTOR phosphorylation while enhancing JNK phosphorylation, leading to the inhibition of cell proliferation and the induction of apoptosis." (PMID 39125630, 2024). "In our study, we observed that DDC not only inhibited mTOR but also elevated LC3-II protein levels in both breast cancer (BC) cell lines, indicating the induction of autophagy." (PMID 38475417, 2024).
breast cancer (continued). "MiR-99a inhibited breast cancer tumorigenesis and progression by targeting the mTOR/p-4E-BP1/p-S6K1 pathway and the cell-cycle pathway through downregulating CDC25A." (PMID 37508580, 2023). "Together, these data provided the rationale for clinical investigations of combined ER and PI3K/AKT/mTOR inhibition in endocrine therapy-resistant ER+ breast cancer." (PMID 36901954, 2023). "This would make sense considering LAT1 expression has already been established in the activation of the mTOR pathway, promoting cell proliferation in breast cancer." (PMID 37819900, 2023). "Elevated mTOR activity in breast cancer cells enhances the expression of c-MYC to increase OGT level via upregulating HSP90A, which protects OGT from degradation by proteasome." (PMID 37838167, 2023). "Everolimus or its analog decreases PI3K, AKT, and mTOR expression levels in esophageal squamous cell carcinoma and breast cancer cells." (PMID 37173935, 2023). "Some combination therapy with mTOR inhibitor and exemestane has significantly prolonged the overall survival (OS) of breast cancer patients with hormone receptor (HR)-positive metastatic breast cancer." (PMID 36831624, 2023). "Recent studies showed that mTOR-mediated resistance to PI3Kβ and Akt inhibitors in breast cancer cells can be reversed by inhibiting the protein levels of Mcl-1." (PMID 37259388, 2023). "High expression of BCAT1 and BCKD genes in breast cancer activates mTOR signaling, and BCAA catabolism is enhanced." (PMID 38028625, 2023). "Anthocyanins possess antioxidant and antimicrobial properties and have been found to inhibit the abnormally activated ERK1/2 and Akt/mTOR signaling pathways in breast cancer cells." (PMID 37432206, 2023). "Long-term CerS4 overexpression promotes breast cancer progression and invasiveness by activating several cancer-related signaling pathways, such as Akt/mTOR, NF-κB, and β-catenin, and inducing EMT." (PMID 37885013, 2023). "In fact, it has been demonstrated that HER2 can increase VEGF protein synthesis by activation of the mTOR/p70S6K cap-dependent translation pathway in human breast cancer cells." (PMID 37397355, 2023). "A recent study suggests that HTyr reduces hypoxia-inducible factor-1 (HIF-1) in MCF-7 breast cancer cell lines by lowering oxidative stress and inhibiting the P13K/Akt/mTOR pathway." (PMID 36836717, 2023). "Increased circulating glucose has been shown to activate mammalian target of rapamycin (mTOR), a significant signaling pathway in breast cancer pathogenesis." (PMID 37626871, 2023). "The keyword analysis and keyword plus analysis revealed resistance to mTOR inhibitors in breast cancer treatment as an emerging research area." (PMID 37637052, 2023). "In recent years, the PI3K/AKT/mTOR signaling pathway has been recognized as an important signaling pathway in breast cancer." (PMID 36959811, 2023). "Another kinase involved in breast cancer is the mechanistic target of rapamycin (mTOR), which regulates proliferation, survival, and cell growth." (PMID 37711177, 2023). "Various cancer pathways, such as nuclear factor kappa B (NF-κB), protein kinase B (Akt)/mammalian target of rapamycin (mTOR), and Wnt/β-catenin, play crucial roles in breast cancer pathogenesis." (PMID 37885013, 2023). "Baselga J, O’Reilly Ke, and Bachelot T’s studies demonstrate the value of mTOR inhibitors in the treatment of breast cancer." (PMID 37637052, 2023). "The role of the PI3K/AKT/mTOR pathway is well known as a trigger for breast cancer, and it is also one of the most important pathways to establish the mechanisms of cancer resistance to treatment." (PMID 37646060, 2023). "Activation of PI3K/Akt/mTOR has been suggested to be required for the adaptation of ERα+ breast cancer to hormone deprivation." (PMID 37172090, 2023).
breast cancer (continued). "In our study, we demonstrated that the overexpression of TMEM97 in breast cancer cells contributed to resistance to tamoxifen treatment, and the overexpressed cells continuously activated the mTOR/S6K1 signaling pathway and the ERα activity." (PMID 38067394, 2023). "In another study, delivery by neutral nanoliposomes of mTOR-siRNA to rats with breast cancer enhanced antitumor efficacy by silencing the oncogenic gene mTOR and promoting apoptosis." (PMID 37416764, 2023). "In recent years, many researchers have initiated investigations into approaches aimed at circumventing the adverse outcomes of mTOR inhibitors during the treatment of breast cancer." (PMID 37637052, 2023). "The role of mTOR in the development and treatment of breast cancer has been acknowledged around the world." (PMID 37637052, 2023). "The PI3K/AKT/mTOR Pathway—A recurrent aberration observed in breast cancer patients is a malfunction in this particular signaling pathway." (PMID 37762375, 2023). "Two of them focused on the use of the mTOR inhibitor everolimus in breast cancer treatment, providing further evidence that everolimus can exhibit anticancer activity when added to endocrine therapy." (PMID 37637052, 2023). "OST inhibits FASN expression in HER2-overexpressing breast cancer cells by regulating the Akt/mTOR pathway." (PMID 36674685, 2023). "Overall, our data revealed that SMYD3 can act as a bridge between the AMPK and mTOR pathways upon neocarzinostatin-induced DNA damage in gastrointestinal and breast cancer cells." (PMID 37998381, 2023). "Abnormalities in the PI3K/AKT/mTOR pathway are also another well-known mechanism of resistance in breast cancer." (PMID 38263984, 2023). "The high frequency of the keyword “apoptosis” suggests that it is of research value to induce apoptosis through the mTOR signaling pathway for the treatment of breast cancer." (PMID 37637052, 2023). "UBE2C is thought to promote breast cancer proliferation by activating the AKT/mTOR signaling pathway, a known key player in metastasis." (PMID 37958776, 2023). "The FDA has approved the mTOR inhibitor everolimus for the treatment of advanced HER2− breast cancer that expresses either ER or PR." (PMID 36979714, 2023). "Clinical evidence has shown that the combination of fulvestrant and the mTOR inhibitor everolimus extended PFS in patients with breast cancer who became resistant to aromatase inhibitor therapy." (PMID 38239650, 2023). "The mTOR signaling pathway is upregulated in many cancers and plays a crucial role in the development of tumors, including breast cancers." (PMID 36674864, 2023). "Recognized as the dominant oncogenic mechanism, PI3K/Akt/mTOR is activated in most breast cancers, and inhibitors of this pathway exhibit therapeutic potential in clinical practice." (PMID 37585411, 2023). "In the future, additional effort should be devoted to elucidating the molecular mechanisms of mTOR signaling and resistance in breast cancer." (PMID 37637052, 2023). "In a murine model of brain xenografts derived from HER2-overexpressed breast cancer with PTEN loss, a combination of PI3K and mTOR inhibitors considerably inhibited tumor growth." (PMID 36980614, 2023). "Among the KEGG enrichment results, the AMPK signaling pathway, cell cycle, mTOR signaling pathway, mitophagy−animal, hepatocellular carcinoma, colorectal cancer, breast cancer were mainly involved." (PMID 37274780, 2023). "Lastly, we review breast cancer therapies targeting mTOR signaling, leptin signaling, blood sugar reduction, and novel immunotherapy targets." (PMID 37626871, 2023). "Taken together, compound XIN-10 is a promising therapeutic approach as a dual PI3K/mTOR inhibitor for the treatment of breast cancer." (PMID 37834269, 2023). "For instance, PI3K/AKT/mTOR signaling has a positive correlation with transcriptomic stemness in breast cancer." (PMID 37490168, 2023).
breast cancer (continued). "For example, by attenuating the stability of mTOR, a kinase complex that phosphorylates AKT, palmitoylation of mTOR mediated by ZDHHC22 reduced AKT signaling in breast cancer cells." (PMID 37759431, 2023). "HER2 activation results in concomitant triggering of the Ras-Raf-MEK-ERK pathway and PI3K-Akt-mTOR pathway, which is crucial for breast cancer cell proliferation, cancer survival, and cancer chemoresistance." (PMID 37894581, 2023). "In recent years, mTOR inhibitors have been approved for treatment of multiple cancers, including renal cell carcinoma, neuroendocrine tumors, and advanced breast cancer, and clinical trials are being conducted in other malignancies." (PMID 37446128, 2023). "In this study, genes in PIK3/AKT/mTOR pathway were deciphered, and PIK3CA mutations were identified as the most frequent genetic alterations observed in 38% of Taiwanese patients with breast cancer." (PMID 37655108, 2023). "In conclusion, we show here that DPP-4 inhibition accelerates breast cancer cell survival by inducing autophagy through CXCL12/CXCR4-mediated mTOR/HIF-1α activation; metformin abrogates such alterations induced by DPP-4 suppression." (PMID 37760498, 2023). "In turn, TAMs were found to secrete CCL2 (C-C motif chemokine ligand 2) which further activates the PI3K/AKT/mTOR axis in tumor cells leading to tamoxifen resistance in breast cancer cells." (PMID 37900137, 2023). "The major downstream signalling pathway Akt is dephosphorylated, consequently down-regulates the mTOR signalling pathway which regulates the cell cycle in SK-BR-3 breast cancer cells (Sehdev, Lai and Bhushan, 2009)." (PMID 38106650, 2023). "Camizestrant also has potential, in combination with CDK4/6 and PI3K/AKT/mTOR inhibitors, to address resistance to current ETs: The highest unmet need in the largest group of patients with breast cancer." (PMID 37725704, 2023). "Our findings reveal METTL3a as an important component of MTC, and suggest the METTL3a–mTOR axis as a potential therapeutic target for breast cancer." (PMID 37589705, 2023). "Simultaneous inhibition of mTOR and treatment of human breast cancer specimens with tamoxifen led to stemness reduction, promotion of mesenchymal to epithelial transition (MET), and sensitivity to chemotherapeutic agents." (PMID 37156724, 2023). "This was due to the approval of several new drugs effective for endocrine resistant breast cancer (mTOR and CDK4/6 inhibitors) emerging during the conduct of this study." (PMID 36441436, 2023). "Using Bibliometrix and VOSviewer, a scientometric analysis of the outputs of publications concerning mTOR and breast cancer was performed for the period 2012-2022." (PMID 37637052, 2023). "A total of 19 patients (22.62%) with advanced breast cancer who received CDK4/6 inhibitors (n=84, ribociclib=47, palbociclib=32, abemaciclib=5) and 3 patients (18.75%) who received an mTOR inhibitor (n=16) were reported to have a PIK3CA mutation." (PMID 37655108, 2023). "Next, we subjected the five target genes as a gene set to GSCA analysis to analyze the mTOR pathway variations, and found that it was significantly correlated with TSC‐mTOR pathway in breast cancer." (PMID 35796646, 2023). "One study observed that miR-214 promotes breast cancer progression by impairing the phosphoinositide 3-kinase (PI3K)/protein kinase B (Akt)/mammalian target of rapamycin (mTOR) signal transduction (PI3K/Akt/mTOR) pathway." (PMID 37374977, 2023). "The PI3K/Akt/mTOR pathway is involved in adipocyte-mediated proliferation and migration of breast cancer cells and can be disrupted by glucocorticoids." (PMID 37337133, 2023). "We also discuss selected trials with agents targeting the PI3K/AKT/mTOR and related pathways as well as the rationale supporting the clinical development of triple combination therapy targeting ER, CDK4/6 and PI3K/AKT/mTOR in ER+ advanced breast cancer." (PMID 36901954, 2023).
breast cancer (continued). "The mTOR pathway interacts with multiple endocrine signaling pathways in breast cancer cells, such as the estrogen receptor pathway and other growth factors involved in tumor progression and resistance to endocrine therapy." (PMID 36672478, 2023). "Over the past decade, thousands of articles have been published on the mechanistic target of rapamycin (mTOR) and its role in breast cancer." (PMID 37637052, 2023). "The crucial role of the PI3K/AKT/mTOR pathway in ER+ breast cancer tumorigenesis and treatment response has been demonstrated in numerous preclinical and clinical studies." (PMID 36901954, 2023). "In another study, TAMs increased CCL2 secretion through M2 polarization and activated the PI3K/Akt/mTOR signaling pathway in breast cancer cells, promoting endocrine resistance." (PMID 37889551, 2023). "Kushenol A suppresses proliferation and induces apoptosis of breast cancer cells by inhibiting PI3K/AKT/mTOR signaling pathway." (PMID 35789211, 2023). "Our findings identify a novel role for DPP-4 inhibition in the promotion of breast cancer survival by inducing CXCL12/CXCR4/mTOR/HIF-1α axis-dependent autophagy." (PMID 37760498, 2023). "The PI3K/AKT/mTOR pathway is frequently activated in breast cancer brain metastases due to PTEN loss of function and frequent PIK3CA, AKT and mTOR activating mutation, as evidenced in our meta-analysis." (PMID 36980614, 2023). "In this study, we explored the effect of OST on breast cancer 4T1 cells in the mTOR/SREBP1/FASN signaling pathway." (PMID 36674685, 2023). "This is consistent with the fact that phosphatidylinositol-3 kinase/mechanistic target of rapamycin (PI3K/mTOR) signaling mediates HER2 downstream signaling and is implicated in the pathogenesis of HER2-overexpressing breast cancers." (PMID 38077030, 2023). "Phosphorylated AKT (Ser473) and phosphorylated mTOR were found to be significantly reduced in two breast cancer cell lines treated with cepharanthine, as were a series of downstream indicators of mTOR." (PMID 37446681, 2023). "ER+/PR+, HER2-breast cancer treated with allosteric mTOR inhibitor, everolimus, which together with Anastrozole, an aromatase inhibitor, has shown improved overall response rates." (PMID 37662839, 2023). "Mammalian target of rapamycin (mTOR) is a parallel signaling pathway that is activated by growth factors and is often hyperactivated in cancer, including breast cancer." (PMID 37163498, 2023). "Due to the large number, heterogeneity, and varying quality of publications related to mTOR and breast cancer, sorting out the present state of the research in this area is critical for both researchers and clinicians." (PMID 37637052, 2023). "There are studies that show quercetin exerts an anticancer effect (breast cancer and pancreatic cancer) by inhibiting mTOR activation." (PMID 37699022, 2023). "In conclusion, we highlight the benefits of incorporating mTOR inhibitors into the current therapy in ER + breast cancer." (PMID 36792625, 2023). "DHEA not only decreases the activation of the PI3K/Akt/mTOR signaling pathway but also increases the expression of Beclin-1, which triggers autophagy of breast cancer cells enhancing the formation of the autophagosome." (PMID 37175104, 2023). "The results revealed that LNT promoted autophagic cell death in breast cancer cells by inhibiting the expression of AKT/mTOR and nuclear factor‐kappaB (NF‐κB) signaling pathway‐related proteins." (PMID 37249285, 2023). "Recent developments in breast cancer research indicate that mTOR inhibitors are a viable method of treatment." (PMID 37626871, 2023). "It has been shown that inhibition of mTOR activity restores the ability of Akt-overexpressing breast cancer cells to respond to tamoxifen." (PMID 37626871, 2023). "Although one of the least characterized proteins in this family, IRS4 has been associated with the hyperactivation of the mTOR and ERK pathways in lung and breast cancer." (PMID 37894790, 2023).